TENT2 (terminal nucleotidyltransferase 2)
Description:
Cytoplasmic poly(A) RNA polymerase that adds successive AMP monomers to the 3'-end of specific RNAs, forming a poly(A) tail. In contrast to the canonical nuclear poly(A) RNA polymerase, it only adds poly(A) to selected cytoplasmic mRNAs. Does not play a role in replication-dependent histone mRNA degradation. Adds a single nucleotide to the 3' end of specific miRNAs, monoadenylation stabilizes and prolongs the activity of some but not all miRNAs.
Synonyms: GLD2; PAPD4; FLJ38499; TUT2; APD4
Tractability: PROTAC: ubiquitination databases record sites on it.
Gene: Protein-coding gene on chromosome 5 (79,611,811 to 79,688,246, forward strand). Ensembl gene ENSG00000164329.
Subcellular location: Cytoplasm; Nucleus
Subcellular location (Human Protein Atlas): Cytosol
Gene Ontology:
Molecular function: poly(A) RNA polymerase activity; protein binding
Biological process: histone mRNA catabolic process; mRNA 3'-end processing; negative regulation of miRNA catabolic process; regulation of gene expression; RNA 3'-end processing; target-directed miRNA degradation
Cellular component: cytoplasm; nuclear RNA-directed RNA polymerase complex; nucleus
Genetic constraint (gnomAD): Loss-of-function variants: 23 observed, 36.93 expected, observed/expected ratio (o/e) 0.62, 90% interval 0.45 to 0.88. The upper end of that interval is the gene's LOEUF score, 0.88, which puts it in group 3 of 6, group 1 being the genes least tolerant of losing a copy. Missense variants: 355 observed, 385.95 expected, observed/expected ratio (o/e) 0.92, 90% interval 0.84 to 1. Synonymous variants: 150 observed, 138.42 expected, observed/expected ratio (o/e) 1.08, 90% interval 0.95 to 1.24.
Homologues: Orthologues: chimpanzee TENT2 (99% identical), macaque TENT2 (99% identical), dog TENT2 (97% identical), pig TENT2 (95% identical), rabbit TENT2 (95% identical), guinea pig TENT2 (94% identical), mouse Tent2 (93% identical), rat Tent2 (92% identical), tropical clawed frog tent2 (62% identical), zebrafish tent2 (49% identical), Drosophila melanogaster wisp (29% identical), Drosophila melanogaster Gld2 (27% identical), and 3 more. Paralogues in human: TUT4 (26% identical), TUT7 (25% identical), TUT1 (20% identical), MTPAP (18% identical).
Diseases named in the same sentence as TENT2 in open-access papers:
TENT2 is named in the same sentence as 14 diseases in open-access papers, as found by Europe PMC text mining. Sharing a sentence is not in itself a finding about the gene and the disease. The quoted sentences say what the papers report.
Anxiety (1 paper, 2025). Intense feelings of nervousness, tension, or panic often arise in response to interpersonal stresses. "The electrophysiological measurements revealed increased excitability of Tent2 KO neurons, and the analyses of mice behavior have shown decreased anxiety and improvement in fear extinction of Tent2 KO mice." (PMID 40101932, 2025). "Electrophysiological measurements revealed increased excitability in Tent2 KO hippocampal neurons, and behavioral analyses showed decreased anxiety and improved fear extinction in these mice." (PMID 40101932, 2025).
cervical cancer (1 paper, 2025). A primary or metastatic malignant neoplasm involving the cervix. "Additionally, human papilloma virus (HPV)-induced cervical cancer is associated with the downregulation of TUT7/ZCCHC6 and the upregulation of TENT2/PAPD4/GLD2 and TENT4A/PAPD7, although the impact of these changes on miRNA 3′ tailing remains to be determined." (PMID 40243428, 2025).
retinal degeneration (1 paper, 2022). Degeneration of the retina. "There are less obvious putative links to potential global drivers of selection for other identified parallel genes CWC27, which is tentatively related to inflammation and retinal degeneration, and TENT2, possibly associated with post‐transcriptional gene regulation and epitranscriptomics." (PMID 35038768, 2022).
TENT2 also shares sentences with these, for which no sentence is quoted: tumor (7 papers); cancer (2); hepatocellular carcinoma (2); Alzheimer disease (1); Angelman syndrome (1); Bardet-Biedl syndrome 18 (1); female infertility (1); hepatitis C virus infection (1); liver cancer (1); liver diseases (1); malignant tumor of the breast (1).